PYCR3 (pyrroline-5-carboxylate reductase 3)
Description:
Oxidoreductase that catalyzes the last step in proline biosynthesis, which corresponds to the reduction of pyrroline-5-carboxylate (P5C) to L-proline using NAD(P)H. Proline is synthesized from either glutamate or ornithine; both are converted to P5C, and then to proline via pyrroline-5-carboxylate reductases (PYCRs). PYCR3 is exclusively linked to the biosynthesis of proline from ornithine.
Synonyms: PYCRL; FLJ13852
Tractability: PROTAC: ubiquitination databases record sites on it.
Gene: Protein-coding gene on chromosome 8 (143,603,210 to 143,609,773, reverse strand). Ensembl gene ENSG00000104524.
Subcellular location: Cytoplasm
Subcellular location (Human Protein Atlas): Cytosol; Cytokinetic bridge; Mitotic spindle
Pathways (Reactome):
Metabolism: Glutamate and glutamine metabolism
Gene Ontology:
Molecular function: protein binding; pyrroline-5-carboxylate reductase activity; identical protein binding
Biological process: L-proline biosynthetic process; L-glutamine catabolic process
Cellular component: cytoplasm; cytosol
Genetic constraint (gnomAD): Loss-of-function variants: 21 observed, 20.57 expected, observed/expected ratio (o/e) 1.02, 90% interval 0.72 to 1.47. The upper end of that interval is the gene's LOEUF score, 1.47, which puts it in group 6 of 6, group 1 being the genes least tolerant of losing a copy. Missense variants: 356 observed, 347.15 expected, observed/expected ratio (o/e) 1.03, 90% interval 0.94 to 1.12. Synonymous variants: 194 observed, 158.08 expected, observed/expected ratio (o/e) 1.23, 90% interval 1.09 to 1.38.
Homologues: Orthologues: chimpanzee PYCR3 (100% identical), dog PYCR3 (88% identical), pig PYCR3 (87% identical), guinea pig PYCR3 (86% identical), mouse Pycr3 (82% identical), zebrafish pycr3 (55% identical). Paralogues in human: PYCR1 (44% identical), PYCR2 (44% identical), NOXRED1 (16% identical).
Diseases named in the same sentence as PYCR3 in open-access papers:
PYCR3 is named in the same sentence as 18 diseases in open-access papers, as found by Europe PMC text mining. Sharing a sentence is not in itself a finding about the gene and the disease. The quoted sentences say what the papers report.
hepatocellular carcinoma (2 papers, 2023 to 2024). A malignant tumor that arises from hepatocytes. "Conversely, PYCR2, while less studied, shows promise as a prognostic biomarker in hepatocellular carcinoma and colorectal cancer, with PYCR3 having limited exploration primarily in nasopharyngeal cancer." (PMID 39125668, 2024). "In Huh7.5 hepatoma cells, the expression of proteins synthesizing proline from P5C (PYCR1, PYCR2, PYCR3) prevails over proline-utilizing proteins (PRODH and PRODH2) and the coordinated action of PYCR3, PRODH, and PRODH2 proteins." (PMID 37189460, 2023).
lung carcinoma (2 papers, 2024 to 2025). "Collectively, our findings provide a novel understanding of the governance of the proline biosynthesis pathway, specifically the PYCR3-mediated branch, in lung cancer cells." (PMID 39075050, 2024). "We further investigated the potential clinical relevance by examining survival data of lung cancer patients with PYCR3-high versus PYCR3-low expression levels." (PMID 39075050, 2024).
glioma (1 paper, 2024). A benign or malignant brain and spinal cord tumor that arises from glial cells (astrocytes, oligodendrocytes, ependymal cells). "Therefore, although our results indicate significant differences only in the PYCR1 isoform, it would seem appropriate to refrain from definite conclusions dismissing the role of PYCR2 and PYCR3 in gliomas until the wider context of the multi-layered metabolic network involved is better understood." (PMID 38275897, 2024).
ovarian carcinoma (1 paper, 2024). A malignant neoplasm originating from the surface ovarian epithelium. "Secondly, the risk of ovarian cancer increased with age in association with MMP3, MMP10, MMP7, TIMP3, POX/PRODH, PYCR1, PYCR3 to indicate degenerative histological changes." (PMID 38397798, 2024).
ovarian neoplasm (1 paper, 2024). A benign, borderline, or malignant neoplasm involving the ovary. "The conversion of glutamine to proline seems to be involved in OC progression since PYCR1 and PYCR3 expression was higher in ovarian neoplasm samples from FIGO III/IV stages as compared to the control group." (PMID 38397798, 2024).
tumor (7 papers, 2016 to 2025). "Three isoforms, PYCR1, PYCR2, and PYCR3, existed and played significant regulatory roles in tumor initiation and progression." (PMID 39125668, 2024). "In both brain and tumor samples, relative mRNA expression of key proline cycle enzymes, that is, POX/PRODH, PYCR1, PYCR2, and PYCR3, were evaluated, along with the expression of genes associated with ECM degradation, i.e., PEPD, MMP-2, and MMP-9." (PMID 38275897, 2024). "Therefore, expression of POX/PRODH, PYCR1, PYCR2, PYCR3, and PEPD was evaluated in both tumor and brain." (PMID 38275897, 2024). "Out of the three studied PYCR isoforms, only PYCR1 turned out to be uniformly upregulated in tumor tissue, which was corroborated by the three assays performed—RT-PCR, Western immunoblot and IHC; minor differences noted in PYCR2 and PYCR3 did not yield statistical significance." (PMID 38275897, 2024).
cancer (5 papers, 2020 to 2024). A tumor composed of atypical neoplastic, often pleomorphic cells that invade other tissues. "Increased expression of PYCR3 has also been identified in a pan-cancer systematic analysis of metabolic adaptations in response to hypoxic environment, again confirming the critical role of proline metabolism in response to oxygen limitation." (PMID 33083024, 2020). "Also, PYCRL/PYCR3 regulates metabolic reprogramming in cancer cells." (PMID 37508547, 2023). "PYCR3 expression was positively correlated with TMB in 11 cancer types and positively correlated with MSI in eight cancer types, while negatively correlated with TMB in COAD and MSI in both COAD and READ." (PMID 39125668, 2024). "In this study, we present that USP9x interacts with the PYCR3 enzyme, promoting its stability through deubiquitination-mediated regulation, thus revealing a previously uncovered role of this DUB as a direct regulator of proline metabolism in cancer cells." (PMID 39075050, 2024). "However, there is no sound evidence implicating PYCR3 in cancer or the PPP." (PMID 33083024, 2020).
PYCR3 also shares sentences with these, for which no sentence is quoted: breast carcinoma (3 papers); asthma (1); colorectal cancer (1); diabetes (1); gastric cancer (1); melanoma (1); nasopharyngeal carcinoma (1); nicotine addiction (1); pancreatic cancer (1); prostate carcinoma (1); triple-negative breast carcinoma (1).